TNF (tumor necrosis factor)
Diseases named in the same sentence as TNF in open-access papers (continued):
Sharing a sentence is not in itself a finding about the gene and the disease.
ulcerative colitis (continued). "The study found that emu oil significantly improved the inflammation level of ulcerative colitis mice, and when used in combination with glycyrrhizin, it showed a stronger regulatory effect on the expression of PPARγ and TNFα, with a synergistic effect on the regulation of PPARγ and TNFα expression." (PMID 37299569, 2023). "Also, berberine exhibited a similar tendency and reduced the IL-1beta, IL-6, and TNF-alpha levels in the study on mice with induced ulcerative colitis, at a dose of 100 mg/kg b.w. i.g.." (PMID 37108329, 2023). "Our findings also reinforced the significance of these inflammatory factors in the incidence and progression of ulcerative colitis, and also demonstrated that SP could drastically lower the iNOS, TNF-α and IL-6 levels in UC mice." (PMID 36838515, 2023). "Our study shows higher levels of SE, CRP, Ag PLT ASPI, Ag PLT TRAP, Ag PLT ADP, Le, PLT, FCP, TNF-α, and IL-6 in patients with ulcerative colitis, when compared to the healthy controls, as well as lower levels of vitamins B12, B6, serum Fe, and transferrin saturation." (PMID 36984554, 2023). "Infliximab has been used as a TNF-α antagonist in the treatment of ulcerative colitis." (PMID 37006260, 2023). "The present result is in harmony with the earlier results of Trivedi and Jena, who showed that β-carotene administration decreased inflammation combined with ulcerative colitis in mice by lowering the colonic contents of immunomodulatory cytokines IL-17, IL-6, and TNFα." (PMID 37018237, 2023). "The C3H7 antigen was increased via treatment with pro-inflammatory cytokine, including interferon-γ and tumor necrosis factor-α in epithelial monolayers, which supports the previous finding that CD44v3 is increased in inflammatory diseases, including ulcerative colitis." (PMID 37176118, 2023). "Further, TNF-α concentration is increased in ulcerative colitis." (PMID 36457188, 2023). "Our results show that the control of MCJ expression impacts on TACE activity and consequently alter the balance between soluble and membrane-bound TNF, constituting a mechanism to regulate cellular responses to environmental changes during chronic ulcerative colitis." (PMID 35705557, 2022). "Andrographolide can block the IL-4R-STAT6 pathway in the colon tissue of mice with ulcerative colitis, effectively inhibit the oxazolinone-induced inflammatory response; reduce inflammatory cell infiltration; and decrease the levels of IL-4, IL-13, and TNF-α." (PMID 36238575, 2022). "Another study demonstrated that the COX-2-PGE2 pathway should be investigated as a target for primary non-responders to tumor necrosis factor (TNF) inhibitor therapy, as well as a prognostic biomarker for TNF inhibitor response in patients with ulcerative colitis." (PMID 35456888, 2022). "This may indicate that anti-TNF treatment may alter the natural disease course for patients with moderate to severe ulcerative colitis." (PMID 36384477, 2022). "Interestingly, TSG-6 was also greatly upregulated in muscle stem cells in response to IFN-γ and TNF-α stimulation and mediated their potently therapeutic efficiency in ulcerative colitis." (PMID 36433947, 2022). "Relevant to the GI tract, the role of TNF in mediating eosinophil recruitment is also specifically highlighted in a study that reported a significant inhibition in eosinophil chemotactic ability in ulcerative colitis patients whose perfusion fluids had been treated with anti-TNF." (PMID 35769556, 2022). "Anti-TNF therapy represented a landmark in medical treatment of ulcerative colitis (UC)." (PMID 35644668, 2022). "Patients with ulcerative colitis have impaired expression of pparγ in the colon and the increased expression of this gene can lead to the inhibition of inflammatory cytokines such as IL-1β and TNF-α." (PMID 34987390, 2021). "Furthermore, another coumarin—osthol relieved the symptoms of ulcerative colitis by reduction of TNF-α level and decrease in the activity of MPO." (PMID 33579030, 2021).
ulcerative colitis (continued). "Therefore, for ulcerative colitis with the existence of IL-1βand TNF-α, the production pathway of HIF-1α is more abundant, and the activation of HIF-1α can induce the production of IL-6, IL-8 and other inflammatory mediators such as iNOS and COX-2." (PMID 32600331, 2020). "Acute ulcerative colitis results in the accumulation of innate immune cells, such as neutrophils and macrophages, and the enhanced secretion of pro-inflammatory cytokines, such as TNFα." (PMID 32290362, 2020). "A previous study also reported that S. boulardii could reduce TNF-α and IL-6 levels in mice ulcerative colitis carcinogenesis model." (PMID 33292591, 2020). "In addition, in people suffering from ulcerative colitis, the levels of TNF-α, IL-6, and IL-1β are greatly increased in the mucosa and serum." (PMID 33204254, 2020). "In this study, the pharmacological stimulation of A3AR, via Cl-IB-MECA, decreased TNF and IL-1β production and attenuated NF-κB p65 activation in colonic tissues in patients with ulcerative colitis, thus corroborating the use of A3AR agonists as an efficacious treatment for IBD patients." (PMID 32575844, 2020). "It is nonetheless worth noting that emerging data on the use of anti-TNF agents in patients with COVID-19 included the description of a case where infliximab was initiated in a 54-year-old female patient for a severe episode of ulcerative colitis." (PMID 33426360, 2020). "The results of the present study were similar to those of a previous study wherein ECM hydrogel delivered via enema for 1 week down-regulated TNFα+/CD68+ macrophages in a rat model of ulcerative colitis, another chronic inflammatory-driven disease of the GI tract." (PMID 32656339, 2020). "During the development of ulcerative colitis, symptoms resulting from an aggravation of the inflammatory process appear, which will result in an exaggerated production of ROS and many cytokines (proinflammatory) such as TNF-alpha, IL-6, and IL-1 beta." (PMID 32565862, 2020). "Although a possible sex influence in the therapeutic effects of anti-TNFα compounds is controversial, a positive female sex influence was already reported in the prognosis of ulcerative colitis in patients treated with infliximab, an anti-TNFα monoclonal antibody." (PMID 33519443, 2020). "Patient 7 with ulcerative colitis developed VL while on TNF-α antagonist treatment." (PMID 31463070, 2019). "Taken together, these findings indicate that TNF-α adversely affects ICC in ulcerative colitis." (PMID 29694505, 2018). "Elevated levels of tumor necrosis factor α (TNFα) in the serum, stools, and mucosa of patients with ulcerative colitis suggest a prominent role for this inflammatory cytokine in the pathogenesis of ulcerative colitis, a premise supported by the effectiveness of anti-TNFα treatments." (PMID 28321512, 2017). "The global phase 3 studies of golimumab [PURSUIT-SC and PURSUIT-maintenance (M)], an anti-tumor necrosis factor-α (anti-TNFα) antibody, have demonstrated clinical efficacy and safety as induction and maintenance therapies in patients with moderate to severely active ulcerative colitis (UC)." (PMID 28324167, 2017). "A recent registry-based Spanish study reported a trend for higher 1-year response and remission rates with adalimumab therapy in anti-TNFα-naïve patients with ulcerative colitis compared with those previously treated with an anti-TNFα agent in routine clinical practice." (PMID 28321512, 2017). "The introduction of anti-tumor necrosis factor-alpha (anti-TNFα) treatment allowed a new option for the management of ulcerative colitis and is expected to decrease the rate of colectomies or at least to extend the time to surgery, compared with standard treatment." (PMID 27497991, 2016).
ulcerative colitis (continued). "The introduction of anti-tumor necrosis factor-alfa (anti-TNFα) treatment allowed a new option for the management of ulcerative colitis and is expected to decrease the rate of colectomies or at least to extend the time to surgery, compared with standard treatment." (PMID 27494322, 2016). "Anti-TNFα treatment is a new, non-invasive option for the management of ulcerative colitis." (PMID 27497991, 2016). "Our patient was being treated with the TNFα blocker adalimumab for his ulcerative colitis." (PMID 27529048, 2016). "For example, taurohyodeoxycholic acid has protective effect on ulcerative colitis in mice, which might be partially due to suppressing pro-inflammatory mediators TNF-α and IL-639." (PMID 26118924, 2015). "In addition, in ulcerative colitis in humans, lamina propria TNF, originating from T-cells and macrophages, strongly correlates with grade of inflammation." (PMID 24497828, 2014). "TNF-α blockers are effective and safe therapies for the induction and maintenance of long-term remission and prevention of treatment by colectomy for patients with refractory ulcerative colitis where conventional treatment was previously ineffective." (PMID 24475168, 2014). "Colonic biopsies from Ulcerative Colitis patients contain increased levels of TNFα." (PMID 27713376, 2010). "Ulcerative colitis rats were treated with 30 mg/kg cycloastragenol, and the gene and protein expression levels of SphK, MIP-1α, B-cell lymphoma 2 (BCL2), BCL2-associated X (BAX), miR-143, NF-κB, tumor necrosis factor (TNF)-α, and active caspase-3 were assessed." (PMID 41304636, 2025). "Patients with moderate to severe ulcerative colitis (UC) have been reported to experience a primary non-response (PNR) rate of 13% to 49% to anti-tumor necrosis factor (anti-TNF) therapy, with an annual loss of response (LOR) reported to range from 10.1% to 13.6%." (PMID 39452572, 2024). "Therefore, EFHD2 might be a potential predictor to guide the clinical treatment of ulcerative colitis with anti-TNF therapy." (PMID 38346956, 2024). "Ethanol extract of PC (100, 200, 400 mg/kg) could prevent colon length shortening and tissue damage, and reduce the levels of inflammatory cytokines in serum of ulcerative colitis mice including interleukin 1β (IL-1β), IL-6, and tumor necrosis factor α (TNF-α)." (PMID 36620922, 2023). "In addition, oral administration of myricetin-3-O-b-D-lactose sodium salt (M10), a derivative of myricetin, also exhibited preventive effect against ulcerative colitis through inhibiting the activation of IL-6 and TNF-α pathway, and phosphorylation of JAK2, STAT3, and NF-κB." (PMID 35805952, 2022). "Our previous study found that BAFF, a new biomarker for IBD, was strongly associated with IBD-related intestinal inflammation and that serum BAFF levels in patients with ulcerative colitis were strongly correlated with Mayo score and TNF-α presented all strong positive correlations." (PMID 35320937, 2022). "As the results of GO analysis, biological processes such as DNA-binding transcription and RNA polymerization may participate in the treatment process; KEGG pathway analysis showed that hub targets were mainly involved in IL-17 signal pathway and TNF signal pathway of ulcerative colitis." (PMID 35966251, 2022). "Moreover, COX-2 inhibition overcame TNFα resistance in these ulcerative colitis patients." (PMID 33776573, 2021). "Additionally, AGN extract prevented epithelial injury in colonic tissues of a murine model of dextran sulfate sodium-induced ulcerative colitis by moderating the activation of inflammatory mediators, such as IL-6, TNF-α, prostaglandin E2 (PGE2), and cyclooxygenase-2 (COX-2)." (PMID 32823713, 2020). "Because anti-TNF-α antibodies are associated with various adverse effects, GWT may represent a potentially safer therapeutic agent for the various types of enterocolitis associated with CD or ulcerative colitis, both of which are well-known IBD." (PMID 29862296, 2018).
ulcerative colitis (continued). "Additionally, increased TNF-α levels have been noted in patients with ulcerative colitis." (PMID 29694505, 2018). "In summary, endogenous colonic LPMs increased their base line and LPS mediated TNF-α secretion by a LITAF dependant pathway when harvested from acutely inflamed colonic tissue suggesting the usefulness of anti-LITAF drug development for the treatment ulcerative colitis." (PMID 21984950, 2011). "Therefore targeting mediators, such as TNFα, which interact with these channels may be a therapeutic option, particularly in Ulcerative Colitis patients and post-infectious diarrhoea-predominant IBS patients." (PMID 27713376, 2010). "Recently, biologics such as UST, Vedolizumab (VDZ, Anti-α4β7) and TNF-a inhibitors Infliximab (IFX) and Golimumab (GLM) have been approved for treating ulcerative colitis and proposed as first-line agents." (PMID 41050686, 2025). "Background/Objectives: In adolescent patients with ulcerative colitis refractory to anti-tumor necrosis factor (TNF) therapy, episodes of acute severe ulcerative colitis (ASUC) require hospitalization or surgery." (PMID 40310056, 2025). "Clinical efficacy of JAK inhibitors such as tofacitinib in ulcerative colitis, along with emerging use in refractory SAPHO cases where TNF-α inhibitors fail or worsen symptoms, further supports the concept of shared cytokine-driven immunopathogenesis." (PMID 40949071, 2025). "This peptide antagonizes tumor necrosis factor-alpha (TNF-α) and exhibits significant anti-inflammatory effects in ulcerative colitis models." (PMID 40137909, 2025). "Tumor necrosis factor-alpha inhibitors, such as IFX and adalimumab, are proinflammatory cytokines that are effective for moderate and severe CD and ulcerative colitis." (PMID 39487903, 2025). "Currently, biological agents including UST (anti-IL-12/IL-23), VDZ (anti-α4β7), and TNF-α inhibitors such as IFX and GLM have been approved for the clinical treatment of ulcerative colitis." (PMID 41050686, 2025). "In ulcerative colitis models, ALO reduces LTB4 and TNF‐α levels and inhibits myeloperoxidase activity and TNF‐α and IL‐1β mRNA expression." (PMID 38888378, 2024). "Concerning the correlations found between TNF-α levels and gut bacterial abundances, Saccharibacteria (former designation: TM7) and Proteobacteria were elevated in patients with ulcerative colitis." (PMID 39684357, 2024). "In the case of acetic acid‐induced ulcerative colitis, the compound diosmin changes the levels of cyclooxygenase‐2 (COX‐II) and tumor necrosis factor (TNF‐α) in a dose‐dependent manner." (PMID 39554345, 2024). "L. plantarum decreased the levels of IL-1β, IL-6, TNF-α, and IFN-γ to enhance the immune barrier and effectively improve ulcerative colitis." (PMID 38540864, 2024). "Existing study has shown that BA can significantly alleviate ulcerative colitis induced by 2,4,6-trinitrobenzene sulfonic acid (TNBS) by blocking the PI3K-AKT signaling pathway, thereby reducing the release of IL-6, TNF-α, and IL-1β." (PMID 39104394, 2024). "Inflammatory cytokines and mediators, such as IL-1b, IL-6, TNF-α, iNOS, and PGE2, are involved in inflammatory responses that induce ulcerative colitis in patients with intestinal inflammation." (PMID 37375714, 2023). "Here, hypoxia and DAMPs released by the necrotic areas, e.g., extracellular histone or tumor necrosis factor alpha (TNFa), can trigger neutrophils to undergo NETosis as it was shown for acute kidney injury (AKI) or ulcerative colitis." (PMID 37372107, 2023). "Olsalazine significantly increased the contents of IL-2, IL-10, IL-22, TGF and EGF in ulcerative colitis rats, and significantly decreased the scores of DAI, CMDI, HS and the contents in IL-7, IL-17, TNF-α, IL-1β and IFN-γ when compared with the model group." (PMID 37610966, 2023). "Recently, biologics such as TNF-a inhibitors infliximab (IFX) and golimumab (GLM) have been approved for treating ulcerative colitis and proposed as first-line agents." (PMID 38203518, 2023).
ulcerative colitis (continued). "Inflammatory factors such as IL-1b, IL-6, TNF-α, iNOS, and COX-2, are frequently expressed in ulcerative colitis models." (PMID 37375714, 2023). "TNF-α at higher doses initiates NET formation, which sustains the inflammatory signals in ulcerative colitis, as shown in neutrophils of patients." (PMID 35242132, 2022). "Multiple studies included in this study showed that vitamin D supplementation effectively reduced the levels of inflammatory factors (IL-6, TNF-α, and CRP) in patients with ulcerative colitis." (PMID 35912148, 2022). "Diosmin treatment was found to alter the levels of tumor necrosis factor (TNF-α) and cyclooxygenase-2 in acetic acid-induced ulcerative colitis (COX-II)." (PMID 35625813, 2022). "As well, suppressing the expression of tumor necrosis factor α (TNF-α), interleukin 8 (IL-8), and interferon-γ (IFN-γ) will lead to a decrease in the ulcerative colitis process." (PMID 35990343, 2022). "For instance, D-carvone protected against dextran sulfate sodium-induced ulcerative colitis in Balb/c mice and LPS-induced RAW cells via the inhibition of COX-2 and TNF-α." (PMID 36294936, 2022). "Decreases IL-1β, TNF-α, MDA, MPO, NF-κB p65, TRAF6, LC3, Beclin1, p62 levels and cell apoptosis; increases SOD activity; and exerts obvious therapeutic effect on rat ulcerative colitis." (PMID 35566359, 2022). "The key inflammatory cytokine TNFα led to the increase in claudin-1 in IEC-18 cells, and increased expression of claudin-1 was observed in ulcerative colitis." (PMID 34573663, 2021). "UC, ulcerative colitis; RCT, randomized clinical trial; RDBCT, randomized double-blinded clinical trial; RDBPCT, randomized double-blinded placebo-controlled trial; TNF-α: tumor necrosis factor α; SC, subcutaneous; IV, intravenous." (PMID 34659943, 2021). "It has been found to be differentially expressed in ulcerative colitis patients and IBD patients that respond to Anti-TNF α." (PMID 33957961, 2021). "A previous randomized control trial demonstrated superior therapeutic effect of PBD in ulcerative colitis patients, compared with 5-ASA and glucocorticoid, with reduced levels of TNF-α and IL-8." (PMID 34059101, 2021). "The bacteriostatic effects induced on Gram+ and Gram- strains, together with the inhibition of COX-2, TNFα, HIF1α, and VEGFA in the colon, suggest the potential of P. mahaleb water extract in contrasting the clinical symptoms related to ulcerative colitis." (PMID 34361576, 2021). "In trinitrobenzenesulfonic acid (TNBS)-induced ulcerative colitis (UC) model, ST36 EA decreased the concentration of TNF-α in serum and MPO activities, and TNF-α mRNA expression in the colon." (PMID 35095910, 2021). "In this regard, the bacteriostatic effects induced on Gram+ and Gram- strains, together with the inhibition of COX-2, TNFα, HIF1α, and VEGFA suggest the potential of P. mahaleb water extract in contrasting the clinical symptoms related to ulcerative colitis." (PMID 34361576, 2021). "The positive effects of 5-ASA and anti-TNF treatments on the size of IBD organoids were observed both on Crohn’s and ulcerative colitis organoid cultures." (PMID 32582690, 2020). "UroA/UAS03 treatment also reduced neutrophil infiltration as evident from myeloperoxidase (MPO) activity as well as serum inflammatory markers such as IL-6, TNF-α, CXCL1, and IL-1β that are hallmarks of ulcerative colitis." (PMID 30626868, 2019). "Cytokines, such as tumor necrosis factor-alpha (TNF-α) and interleukin (IL), play important roles in the inflammatory process of ulcerative colitis." (PMID 29694505, 2018). "Our study provides a regulatory mechanism of TNF-α in ICC and emphasizes the importance of the NF-κB signaling pathway in development of ulcerative colitis." (PMID 29694505, 2018). "Since cytokines play a critical role in ulcerative colitis, we examined the effect of MALT1 knockdown combined with MI-2 treatment on the expression of cytokines, including TNF-α and IL-17α, -22, and -1β, in intestinal tissue." (PMID 30249750, 2018).